PPARG (peroxisome proliferator activated receptor gamma)
Diseases named in the same sentence as PPARG in open-access papers (continued):
Sharing a sentence is not in itself a finding about the gene and the disease.
bladder cancer (continued). "15d-PGJ2, a PPARγ agonist, induces the production of ROS in bladder cancer cells." (PMID 32328200, 2020). "Taken together, the novel structural aspects of the PPARγ LBD Q286E mutant could explain the PPARγ transactivation in a ligand-independent manner and the modulation of its pro-tumorigenic role in bladder cancer." (PMID 33266062, 2020). "However, the precise mechanisms affecting the PPARγ signaling pathway in response to lipid metabolism in bladder cancer remain poorly understood." (PMID 32328200, 2020). "Taken together, basic research and clinical trials are needed to determine whether PPARγ is a promising biomarker for bladder cancer diagnosis and an effective target for bladder cancer treatment." (PMID 32328200, 2020). "In our studies, treatment with TG did result in the differentiation of the As3+-transformed cells based upon morphological changes and induced the expression of PPARγ as well as FOXA1 both of which are factors known to drive luminal differentiation of bladder cancer cell lines." (PMID 32822399, 2020). "Recently, a study showed that three recurrent mutations, PPARγM280I, PPARγT475M and PPARγI290M, modify the conformation and structural dynamics of the protein, and subsequently affect the ligand binding domain of PPARγ, resulting in a change in protein activity in luminal bladder cancer." (PMID 32328200, 2020). "Troglitazone (TGZ), a PPARG agonist, was reported to induce G2/M cell cycle arrest through activation of p38 mitogen-activated protein kinase in renal cell carcinoma, and similar effects were also seen in bladder cancer cells." (PMID 33029111, 2020). "In addition, in a study involving 117 paraffin slice specimens of bladder cancer, researchers found that PPARγ was more likely to be upregulated in the Ta-T1 phase of tumors than in invasive tumors in the T2-T4 phase." (PMID 32328200, 2020). "Recent studies suggest both tumor suppressive and oncogenic role of PPARγ in bladder cancer." (PMID 30845932, 2019). "In aggregate, these data suggested that PPARγ might be a favorable prognostic factor in bladder cancer patients." (PMID 30845932, 2019). "However, the full PPARγagonists including pioglitazone and rosiglitazone significantly suppressed cell growth in Umuc-3 and 5637 cells, suggesting PPARγ activation suppresses proliferation of bladder cancer cells in vitro." (PMID 30845932, 2019). "We showed that PPARγ was a favorable prognostic factor in patients with bladder cancer." (PMID 30845932, 2019). "This study suggested that transactivation of PPARγ could be served as a potential strategy for the chemoprevention and therapeutic treatment of bladder cancer." (PMID 30845932, 2019). "On the contrary, multiple studies have indicated that PPARγ activation might be also a promising approach to suppress bladder cancer." (PMID 30845932, 2019). "Regardless, decreasing PPARγ expression may potentially alter bladder cancer migration and invasive abilities." (PMID 28348577, 2017). "Together, our data propose that the PPARγ/RXRαS427F pathway may serve as a viable therapeutic node for activating immunosurveillance, enhancing response to immunotherapies in bladder cancer." (PMID 28740126, 2017). "Therefore, RXRαMUT preferentially and constitutively interact with PPARγ to activate PPARγ/RXRα-mediated signaling activity in the bladder cancer cells." (PMID 28740126, 2017). "While the role in adipocytes and insulin sensitivity is well understood, the effects of PPARγ activation in many other cell types remain unclear including bladder cancer." (PMID 28348577, 2017). "We also explored the possibility that RXRA or PPARG alterations may be restricted to subtypes of bladder cancer classified by expression and genomic profiles." (PMID 28740126, 2017). "Furthermore, chemokines CCL2 and CXCL10, which contribute to immunosurveillance, were induced by shRNAs of PPARγ and RXRα in HT-1197 bladder cancer cells bearing endogenous RXRαS427F." (PMID 28740126, 2017).
bladder cancer (continued). "Thus, both PPARD and PPARG contribute to mutant RXRA-mediated transcriptional hyperactivity in human bladder cancer cells and appear to have redundant function." (PMID 29143738, 2017). "In support of this, we found that cytokine and immune pathways were significantly suppressed by PPARγ or RXRαS427F/Y in the engineered T24 bladder cancer cell lines indicating that tumor autonomous signaling may influence the host immune response." (PMID 28740126, 2017). "Potentially, PPARγ signaling in bladder cancer cells may provide a tumor microenvironment that allows for de novo lipogenesis for the use of increasing tumor mass and energy usage." (PMID 28348577, 2017). "Collectively, we posit that this resistance phenotype may be reversed by therapeutic targeting of PPARγ/RXRα offering a therapeutic approach to sensitizing bladder cancer with activated PPARγ/RXRα pathway to immunotherapies." (PMID 28740126, 2017). "However, we did observe a significant reduction of PPARγ DNA-binding activity in the bladder cancer tissues detected by ELISA analysis." (PMID 27779188, 2016). "RT-PCR analysis indicated an increase of PPARγ mRNA level in the bladder cancer tissue." (PMID 27779188, 2016). "In conclusion, our study suggested that simvastatin could inhibit proliferation and EMT and trigger cell cycle arrest at G0/G1 phase via the PPARγ signalling pathway in bladder cancer cells." (PMID 27779188, 2016). "Additionally, in situ hybridization showed that PPARγ gene was often amplified in bladder cancer specimens." (PMID 26770009, 2015). "Indeed, treatment with a PPARγ agonist rosiglitazone or PPARγ overexpression resulted in significant increases in bladder cancer cell migration and invasion." (PMID 26770009, 2015). "Earlier studies conversely showed that PPARγ agonists inhibited bladder cancer cell growth." (PMID 26770009, 2015). "PPARγ is highly expressed in tumor samples from different sites, including bladder cancer." (PMID 23409107, 2013). "We provide new evidence on the role of PPARG in initiation and maintenance of bladder cancer." (PMID 23114535, 2012). "Thus, depending on differentiated state of the cells, we showed that ciglitazone individual treatment induced G2/M phase cell cycle arrest but triggered apoptosis only in T24 high grade bladder cancer cells through PPARγ activation-independent mechanisms." (PMID 22174792, 2011). "Also,a recent study showed that the specific PPARγ agonist rosiglitazone is a strongpromoter of hydroxybutyl(butyl)nitrosamine-induced bladder cancer in rats." (PMID 19197366, 2008). "PPARγ expression was shown to be higher in high-grade bladder cancer compared to low-grade cancer." (PMID 15583697, 2005). "However, therapeutic targeting of PPARγ in bladder cancer remains controversial, as its effects may vary depending on the tumor context and the specific PPARγ ligands used." (PMID 40290121, 2025). "However, the molecular components that regulate PPARG gene expression in bladder cancer remain unclear." (PMID 37250326, 2023). "However, the molecular mechanisms that regulate PPARG expression in luminal bladder cancer remain unclear." (PMID 37250326, 2023). "Notably, the present study provided evidence that SNHG1 promotes MDM2 expression by binding to miR-9-3p to promote PPARγ ubiquitination and downregulate PPARγ expression, thereby resulting in elevation of bladder cancer cell proliferation in vitro and tumorigenesis in vivo." (PMID 36230661, 2022). "Interestingly, we found PPAR signaling was significantly activated in gene cluster A, but the previous studies have reported PPARγ signaling could increase the incidence and progression of bladder cancer, which might lead to worse prognosis." (PMID 35418978, 2022). "However, further studies are required on the mechanism of PPARγ in bladder cancer." (PMID 36230661, 2022). "However, the expression and function of PPARγ in bladder cancer seem to be controversial." (PMID 32328200, 2020).
bladder cancer (continued). "In addition, overexpression of GATA3 and FOXA1 may cooperate with PPARγ activation to drive trans-differentiation of a basal bladder cancer cells to a luminal phenotype." (PMID 30845932, 2019). "This study reported the tumor-suppressive effect of PPARγ agonists in bladder cancer, suggesting that transactivation of PPARγ could be served as a potential strategy for the chemoprevention and therapeutic treatment of bladder cancer." (PMID 30845932, 2019). "However, more studies need to be performed to understand the role of PPARγ in bladder cancer." (PMID 28348577, 2017). "Therefore, regulating levels of PPARγ expression in the urinary bladder may have implications for targeting bladder cancer, particularly regarding metastasis and cancer cell progression." (PMID 28348577, 2017). "Although we cannot completely exclude the potential role of PPARγ/RXRα in transformed cell autonomous phenotypes, our data suggest that induction of microenvironmental reprogramming favored by tumorigenesis is a key function of PPARγ/RXRα activation in bladder cancer." (PMID 28740126, 2017). "Bilirubin may offer a therapeutic potential because it activates PPARα and suppresses PPARγ, and fenofibrate has not been associated with bladder cancer." (PMID 28348577, 2017). "Furthermore, PPARγ may provide the tumor-promoting microenvironment by de novo synthesis of nutrients that are needed for bladder cancer development." (PMID 28348577, 2017). "It has been proposed that PPARγ agonists are not free from side effects including edema, headache, hypoglycemia, myalgia, HF, weight gain, bone fractures, increased risk of MI and mortality, and possibly bladder cancer." (PMID 27293418, 2016). "Thiazolidinediones are peroxisome proliferator-activated receptor gamma (PPARγ) agonists and improve insulin sensitivity although the circulation of some of them has been suspended in Europe due to concerns about cardiovascular safety and increases in bladder cancer incidence." (PMID 23363332, 2013). "In the PPARγ/PTEN/AKT signaling pathway, upregulation of PPARγ and PTEN proteins inhibits the AKT-activated cascade response, as demonstrated in both pancreatic cancer and bladder cancer." (PMID 41300337, 2025). "In bladder cancer, SNHG1 promotes tumor cell proliferation and inhibits apoptosis by regulating PPARγ ubiquitination." (PMID 37686677, 2023). "Since high PPARG expression is a feature of luminal MIBC, we sought to identify a luminal bladder cancer cell line with high endogenous levels of PPARG to use for the assay." (PMID 37250326, 2023). "The PPARγ-independent induction of apoptosis by 15d-PGJ2 has also been demonstrated in prostate and bladder carcinoma cells." (PMID 35954274, 2022). "Accordingly, PPARγ activation gave rise to inhibition of proliferation of 9 bladder cancer cell lines All in all, the SNHG1/miR-9-3p/MDM2/PPARγ axis was involved in bladder cancer progression." (PMID 36230661, 2022). "Disease enrichment analysis from the TTD database showed that the target genes of LA, PPARG, and PTGS2 were related to the occurrence and development of bladder cancer (as shown in the black box)." (PMID 35656081, 2022). "From our data, the mRNA expressions of PPARG and PTGS2 were up-regulated in two bladder cancer cell lines in comparison with the normal cells SV-HUC-1." (PMID 35656081, 2022). "The transcription factors PPARγ, FOXA1, and GATA3 play a role in the establishment of the luminal subtype of bladder cancer." (PMID 32822399, 2020). "The correlation of PPARγ activation with PI3K-Akt pathway was evaluated with RNA sequencing data from the TCGA cases and 30 human bladder cancer cell lines." (PMID 30845932, 2019).
bladder cancer (continued). "The activation of PPARγ by mutations may, therefore, result in PPARγ-dependence not only in bladder cancer, but also in other types of cancer, reinforcing the importance of developing new pharmacological approaches targeting the ligand-independent activity of PPARγ in tumors." (PMID 30651555, 2019). "We further confirmed this dependence using PPARγ-specific antagonist T0070907 in human bladder cancer lines HT-1197 carrying the endogenous RXRαS427F, and 5637 and UM-UC941 lines bearing PPARγ amplifications." (PMID 28740126, 2017). "We further performed similar PPARγ and CD8 staining in an independent larger cohort of bladder tumor samples (bladder cancer meta-dataset)." (PMID 28740126, 2017). "Further to the PPARγ-independent effects of TGZ and 15dPGJ2 discovered in prostate and bladder carcinoma, our study also demonstrates that TGZ and 15dPGJ2 induce growth inhibition via different mechanisms." (PMID 16519808, 2006). "It was found that ISO down-regulated the expression of PPARγ, PTEN, AKT, and CA9 proteins in the PPARγ/PTEN/AKT signaling pathway in bladder cancer cells, inhibited the activity of proliferation-related proteins, and thus, inhibited the occurrence and progression of bladder cancer." (PMID 40507124, 2025). "The absence of EMP1 stimulates bladder cancer cell migration by activating the PPARγ signaling pathway." (PMID 40612666, 2024). "Additionally, the combination of simvastatin with romidepsin synergistically killed bladder cancer cells, with mechanisms involving ER stress induction, AMPK activation, histone acetylation, and enhanced PPARγ expression." (PMID 39101139, 2024). "Previous literature has shown that PPARG, as a nuclear receptor, is attenuated in basic bladder cancer with muscle invasive, but over-expressed in non-muscle invasive luminal bladder cancer." (PMID 37197716, 2023). "We therefore utilized CRISPR knockin technology to create a transgenic luminal bladder cancer cell line engineered to express GFP and PPARG proportionally, so that fluorescence could be used as a readout to identify endogenous regulators of PPARG expression." (PMID 37250326, 2023). "Moreover, qRT-PCR analysis showed that the mRNA expression of PPARG and PTGS2 was up-regulated in two bladder cancer cell lines in comparison with the normal cells SV-HUC-1." (PMID 35656081, 2022). "SZY-200 could down-regulate the expressions of PPARG and PTGS2 which were related to the occurrence and development of bladder cancer." (PMID 35656081, 2022). "Our study elucidated that SNHG1 promotes MDM2 expression by binding to miR-9-3p to promote PPARγ ubiquitination and downregulate PPARγ expression and that SNHG1 plays an important role in bladder cancer and provides a potential therapeutic target for bladder cancer." (PMID 36230661, 2022). "Also in a bladder cancer cell line, VEGF expression was upregulated in response to stimulation with PPARα, PPARβ/δ, and PPARγ agonists, while another bladder cancer cell line responded only to PPARβ/δ activation." (PMID 32785018, 2020). "Interestingly, PPARγ Q286E found in bladder cancer induces a constitutively active conformation of PPARγ LBD and thus abnormal activation of PPARγ/RXRα pathway, which suggests tumorigenic roles of PPARγ in bladder cancer." (PMID 33266062, 2020). "The effect of PPARγ activation on cell proliferation, cell cycle, and cell apoptosis were determined with the agonists (rosiglitazone and pioglitazone), the inverse agonist (T0070907), and the antagonist (GW9662) in Umuc-3 and 5637 bladder cancer cells." (PMID 30845932, 2019). "If PP5 is a positive modulator of PPARγ in the bladder epithelium, then reducing PP5 expression may serve as an alternative therapeutic target to hinder bladder cancer progression." (PMID 28348577, 2017).
bladder cancer (continued). "Another study showed that the T24 bladder cancer cell line expresses PPARγ and high levels of the nuclear receptor glucocorticoid receptor β (GRβ), which also showed higher migration rates than the UMUC-3 cells that have low PPARγ and GRβ expression." (PMID 28348577, 2017). "To this end, we identified PPARγ active and inactive tumors using GLMnet74 (refer to “Methods”) across an independent cohort of 127 chemotherapy naïve MIBC (TURBT meta-dataset) and the MD Anderson bladder cancer data set (GSE48075)." (PMID 28740126, 2017). "Importantly, human bladder cancer samples appear to express both PPARD and PPARG and our data suggest both are activated by mutant RXRA and play a role in transcriptional hyperactivity in human bladder cancer cells." (PMID 29143738, 2017). "We probed the potential mechanism(s) that promote the non-inflamed immuno-phenotype by PPARγ/RXRαS427F/Y in bladder cancer." (PMID 28740126, 2017). "In the future, therapies that target PPARγ, or possibly PP5, may prove to be useful in bladder cancer treatment, particularly among diabetic patients that require long-term health management." (PMID 28348577, 2017). "Our data indicates RGZ and PGZ would be useful candidates to study the role of up-regulated PPARγ in prostate and bladder carcinoma as these ligands do not exhibit PPARγ-independent growth inhibitory effects." (PMID 16519808, 2006). "The effects of TGZ (50 and 100 μM), CGZ (40 μM), RGZ (10 μM), PGZ (20 μM) and 15dPGJ2 (5.6 and 10 μM) on the TSU-Pr1 bladder carcinoma cell line were examined in the presence or absence of the highly selective PPARγ antagonist GW9662 (10 μM)." (PMID 16519808, 2006). "Similarly, PPARG did not emerge as significantly upregulated gene by GATA3 overexpression in 5637 basal bladder cancer cells." (PMID 37250326, 2023). "By using a luminal bladder cancer cell line with high PPARG expression, we likely selected a system that lacked activity of many of the regulatory mechanisms that actively suppress PPARG gene expression, therefore limiting our ability to identify these mechanisms using a gene knockout system." (PMID 37250326, 2023). "Peroxisome proliferator-activated receptor gamma (PPARG) could induce cell cycle arrest, terminal differential, and anti-inflammatory, and induce G2/M cell cycle arrest by activating P38 in renal cancer and bladder cancer." (PMID 34384030, 2021). "In addition, lower levels of PPARγ amplification were detected in non-muscle-invasive bladder cancer samples compared to muscle-invasive samples (16.7% versus 46.7%, resp)." (PMID 28348577, 2017). "The vast majority of PPARγ/RXRα active tumors were presented in Cluster I, a subset of luminal bladder cancer, suggesting PPARγ/RXRα activation may contribute to lack of response to immunotherapy." (PMID 28740126, 2017). "The aim of this study is to investigate crosstalk between these two signalling axes as they share some common downstream signalling effectors and evaluate whether combination of PPARγ agonist and an EGFR inhibitor may overcome resistance to EGFR therapy in bladder cancer." (PMID 23409107, 2013). "In addition, LA alone could inhibit the proliferation of bladder cancer cells, while SZY-200 downregulates the expressions of the peroxisome-proliferator-activated receptor gamma (PPAR-γ) and prostaglandin-endoperoxide synthase 2 (PTGS2) genes involved in the development of bladder cancer." (PMID 40863333, 2025). "Although, not all recently identified gain-of-function PPARγ mutants have extensively been characterized and even affect different domains in the protein, at least some of the mutants have implications for “classical” transactivation of PPARγ target genes in bladder cancer." (PMID 33716977, 2021).